GINS2 (GINS complex subunit 2)
Description:
Required for correct functioning of the GINS complex, a complex that plays an essential role in the initiation of DNA replication, and progression of DNA replication forks. GINS complex is a core component of CDC45-MCM-GINS (CMG) helicase, the molecular machine that unwinds template DNA during replication, and around which the replisome is built.
Synonyms: PSF2; HSPC037; Pfs2
Tractability: Small molecule: a structure with a bound ligand is known; it has a binding pocket of medium quality. PROTAC: UniProt records ubiquitination sites on it; ubiquitination databases record sites on it.
Gene: Protein-coding gene on chromosome 16 (85,676,198 to 85,690,073, reverse strand). Ensembl gene ENSG00000131153.
Subcellular location: Nucleus; Chromosome
Subcellular location (Human Protein Atlas): Nucleoplasm
Pathways (Reactome):
DNA Replication: Unwinding of DNA
Gene Ontology:
Molecular function: protein binding
Biological process: DNA replication; double-strand break repair via break-induced replication
Cellular component: CMG complex; GINS complex; nucleus; nucleoplasm; chromosome; nuclear lumen
Genetic constraint (gnomAD): Loss-of-function variants: 11 observed, 9.89 expected, observed/expected ratio (o/e) 1.11, 90% interval 0.7 to 1.75. That is too few expected variants to judge how well the gene tolerates losing a copy. Missense variants: 195 observed, 145.94 expected, observed/expected ratio (o/e) 1.34, 90% interval 1.19 to 1.5. Synonymous variants: 76 observed, 55.13 expected, observed/expected ratio (o/e) 1.38, 90% interval 1.14 to 1.67.
Homologues: Orthologues: chimpanzee GINS2 (99% identical), macaque GINS2 (99% identical), dog GINS2 (95% identical), rat Gins2 (93% identical), mouse Gins2 (92% identical), pig GINS2 (88% identical), tropical clawed frog gins2 (84% identical), guinea pig GINS2 (83% identical), zebrafish gins2 (79% identical), rabbit GINS2 (51% identical), Drosophila melanogaster Psf2 (42% identical), Caenorhabditis elegans psf-2 (35% identical).
Diseases named in the same sentence as GINS2 in open-access papers:
GINS2 is named in the same sentence as 66 diseases in open-access papers, as found by Europe PMC text mining. Sharing a sentence is not in itself a finding about the gene and the disease. The quoted sentences say what the papers report.
breast carcinoma (11 papers, 2011 to 2022). "In breast cancer patients, elevated GINS2 transcript level was associated with poor relapse-free and distant metastasis-free survival." (PMID 30042885, 2018). "Some reports show that GINS2 is also involved in the occurrence and progression of various cancers, including breast cancer, ovarian cancer, cervical cancer, leukemia, and glioma." (PMID 36466552, 2022). "The downregulation of GINS2 expression can inhibit the growth of breast cancer cells by activating endogenous DNA damage." (PMID 36466552, 2022). "Previous studies have also shown that GINS2 is highly expressed in other cancers, such as breast cancer, cervical cancer and intrahepatic cholangiocarcinoma." (PMID 32181475, 2020). "GINS2 is upregulated in a variety of aggressive tumors, such as leukemia, breast cancer, and cervical cancer." (PMID 32626512, 2020). "Several studies have shown that GINS2 is abnormally expressed in many tumours, such as breast cancer, leukaemia, lung adenocarcinoma, and so on." (PMID 32181475, 2020). "Previous studies indicated that GINS2 is highly expressed in breast cancer 11, ovarian cancer 12, leukemia 13,14, gliomas 15, and cervical cancer." (PMID 32626512, 2020). "Known breast cancer susceptibility genes like TPX2, AURKA, TK1 and BIRC5 are among the top 7 global drivers (the other 3 top drivers are GINS2, COX4NB and NUP93)." (PMID 21806811, 2011). "In addition, GINS2 is related to the invasive characteristics of breast cancer, and it is presumed that GINS2 is related to the metastasis of lung cancer." (PMID 33391406, 2021). "GINS2 was revealed to be up‐regulated in leukaemia, breast cancer and cervical cancer." (PMID 32596993, 2020). "Together with its expression in breast cancer, GINS2 is speculated to be a potential metastasis-promoting gene, and its overexpression may participate in lung adenocarcinoma metastasis." (PMID 24137407, 2013). "In conclusion, the overexpression of AURKB, GINS2, MCM10, UHRF1, POLE2, SPC24, and E2F2 in HER2-positive breast cancer patients with ALR showed that these hub genes could be potential prognostic biomarkers in such patients." (PMID 33013420, 2020). "Indeed, there were 5 genes that were present in our list and in the up regulated list for breast cancer (RAP2C, SPN, GINS2, ESPL1 and IRF7)." (PMID 29108258, 2017).
cervical cancer (11 papers, 2018 to 2025). A primary or metastatic malignant neoplasm involving the cervix. "GINS2 upregulation was associated with poor prognosis and reduced survival in early-stage cervical cancer." (PMID 30042885, 2018). "GINS2 was shown to be upregulated in the cervical cancer cell lines and tumor specimens compared to the normal control." (PMID 32953881, 2020). "Similarly, patients with higher GINS2 expression had shorter overall survival than patients with low GINS2 expression in early-stage cervical cancer." (PMID 33391406, 2021). "Specifically, GINS2 (Psf2) overexpression has been reported in various human malignancies, including head and neck squamous cell carcinomas (HNSCC), epithelial ovarian cancer, Osteosarcoma, cervical cancer, often correlating with aggressive tumor characteristics and poor patient prognosis." (PMID 41322418, 2025).
pancreatic cancer (8 papers, 2020 to 2025). "Previous studies indicate that downregulation of GINS2 causes decreased cell vitality, promotes apoptosis and the inhibition cell cycle progression in pancreatic tumor cells." (PMID 35069907, 2022). "However, to the best of our knowledge, the association between GINS2 and the progression of pancreatic cancer has still remained obscure." (PMID 32626512, 2020). "The mechanism underlying this phenomenon indicated that GINS2 may be highly significant for the treatment of pancreatic cancer." (PMID 32626512, 2020). "Moreover, bioinformatics analysis was utilized to investigate the association between GINS2 and tumor growth, in order to identify molecular mechanisms on the pathogenesis of pancreatic cancer." (PMID 32626512, 2020). "The downregulation of GINS2 in pancreatic cancer cells resulted in a significant downregulation of CDK4/6." (PMID 38467631, 2024). "GINS complex subunit 2 (GINS2) serves as an oncogene in cancer genesis by enhancing cell growth and repressing cell apoptosis in various cancers, including thyroid, lung, and pancreatic cancers." (PMID 34288816, 2021). "GINS2 expression in pancreatic cancer cells transfected with siRNA was significantly lower compared with NC." (PMID 32626512, 2020). "For the purpose of studying the role of GINS2 in pancreatic cancer, GINS2 siRNA was prepared and transfected into pancreatic cancer cells." (PMID 32626512, 2020). "In summary, we demonstrated that GINS2 interference inhibited the cell viability, promoted cell apoptosis, and induced cell cycle arrest in pancreatic cancer cell lines via the MAPK/ERK pathway." (PMID 32626512, 2020). "Taken together, our outcomes indicated that GINS2 influences the cell viability, cell apoptosis, and cell cycle of pancreatic cancer cell lines via the MAPK/ERK pathway." (PMID 32626512, 2020). "At 48 and 72 h, the number of pancreatic cancer cells in the GINS2 siRNA group was noticeably lower than that in NC group." (PMID 32626512, 2020). "Subsequent experiments on the effects of GINS2 knockdown should be carried out using the effective GINS2 siRNA in pancreatic cancer cells." (PMID 32626512, 2020). "GINS2 knockdown also inhibits cell viability and induces cell cycle arrest in pancreatic cancer cells." (PMID 33061798, 2020). "In order to determine the function of GINS2 in human pancreatic cancer, the knockdown of GINS2 was achieved by GINS2 siRNA." (PMID 32626512, 2020). "Altogether, our data indicated that GINS2 affects the cell proliferation, apoptosis and cell cycle in pancreatic cancer cells via MAPK/ERK pathway." (PMID 32626512, 2020). "In order to confirm the mechanisms of GINS2 interference inhibiting cell proliferation and promoting apoptosis in pancreatic cancer cells, we detected the gene expression profiling of NC group and GINS2 siRNA group in PANC-1 cells." (PMID 32626512, 2020). "Indeed, GINS2, as a novel unraveled oncogene, has been reported to affect cell viability, apoptosis, and cell cycle progression in pancreatic cancer." (PMID 35069907, 2022). "To further confirm our hypothesis, we performed microarray, bioinformatics, and Western blotting assays to indicate whether GINS2 affects the ERK pathway to alter the biological behaviors of pancreatic cancer cell lines." (PMID 32626512, 2020). "We next evaluated the effects of GINS2 on cell apoptosis in pancreatic cancer cells." (PMID 32626512, 2020). "These outcomes indicated that GINS2 may influence the function of pancreatic cancer cells by regulating MAPK/ERK pathway." (PMID 32626512, 2020). "GINS2 could stimulating the ERK/MAPK signaling to promote the pancreatic cancer development." (PMID 40859234, 2025). "However, the role of GINS2 in pancreatic cancer has still remained elusive." (PMID 32626512, 2020). "However, it has still remained elusive whether GINS2 affects cell viability, cell apoptosis, and cell cycle of pancreatic cancer through the MAPK/ERK pathway." (PMID 32626512, 2020).
pancreatic cancer (continued). "GINS2 is a member of the GINS complex and participates in DNA replication and cell cycle regulation in most tumors, such as pancreatic cancer 41, bladder cancer 71, and lung cancer." (PMID 33061798, 2020). "However, the effects of GINS2 on pancreatic cancer patients have not been reported yet." (PMID 32626512, 2020).
glioma (7 papers, 2019 to 2024). A benign or malignant brain and spinal cord tumor that arises from glial cells (astrocytes, oligodendrocytes, ependymal cells). "To explore the association between TMZ treatment and GINS2 expression, we treated glioma cells with 200 μM TMZ for increasing time durations." (PMID 38467631, 2024). "In light of these findings, we illustrated a graphical abstract showcasing the regulatory role of GINS2 in TMZ chemosensitivity through the EGR1/ECT2 axis in glioma cells." (PMID 38467631, 2024). "Pal and BIX-02189 are novel inhibitors of GINS2 that synergistically inhibited glioma proliferation with TMZ." (PMID 38467631, 2024). "The results of the CCK-8, clone formation, tumor sphere formation, scratch, and Transwell migration and invasion assays showed that GINS2 promoted the malignant phenotype of glioma cells and attenuated their sensitivity to TMZ." (PMID 38467631, 2024). "To explore the role of GINS2 in the development of glioma, we examined the mRNA and protein expression of GINS2 in seven glioma cell lines." (PMID 38467631, 2024). "Compared with LGGs, GINS2 expression was higher in HGGs along with higher malignancy (P < 0.05), indicating that GINS2 expression correlated with glioma grade." (PMID 38467631, 2024). "Here, we report that GINS2 was upregulated in TMZ-treated glioma cells and co-localized with γH2AX, indicating its participation in TMZ-induced DDR." (PMID 38467631, 2024). "The CCK-8 and colony formation assays showed that upregulating ECT2 reversed the GINS2 KO-mediated decrease in the proliferative capacity and colony formation ability of glioma cells." (PMID 38467631, 2024). "This study demonstrates that GINS2 affected the proliferation, clone formation, stemness, migration, and invasion of glioma cells, as reported in other cancers as well." (PMID 38467631, 2024). "We predicted two GINS2 inhibitors with the most minor scores in both the TCGA and Chinese Glioma Genome Atlas databases: Palbociclib (Pal) and BIX-02189." (PMID 38467631, 2024). "Further, we screened Palbociclib/BIX-02189 which dampens GINS2 expression and synergistically inhibits glioma cell proliferation with TMZ." (PMID 38467631, 2024). "Using CMap, we screened a GINS2 inhibitor that synergistically inhibited the proliferation of glioma cells along with TMZ." (PMID 38467631, 2024). "Overexpression of BUB1 contributes to the morphological progression of clear cell renal carcinoma Shen YL’s research showed that GINS2 can accelerate the growth of glioma cells." (PMID 37745716, 2023). "In addition, suppressing the expression of GINS2 significantly reduced the proliferation and tumorigenicity of glioma cells, probably via the action of cell cycle-related genes." (PMID 38467631, 2024). "Similarly, the expression of GINS2 mRNA was significantly higher in collected glioma samples than paraneoplastic tissues, as evidenced by reverse transcription–quantitative PCR (RT–qPCR) (P < 0.05)." (PMID 38467631, 2024). "GINS2 inhibitors may effectively suppress glioma cell proliferation by enhancing the TMZ sensitivity of the cells." (PMID 38467631, 2024). "In addition, Pal/BIX-02189 and TMZ synergistically inhibited glioma cell proliferation, at least in part by inhibiting GINS2 and DDR." (PMID 38467631, 2024). "While there is abundant research reporting high expression of GINS2 in various tumors, including gliomas, promoting tumor cell proliferation and migration, inhibiting apoptosis, and regulating the cell cycle, it can serve as a new diagnostic marker and therapeutic biomarker for tumors." (PMID 39458936, 2024). "GINS2 may regulate the sensitivity of glioma cells to TMZ, which in turn also influences the malignant phenotype of cells." (PMID 38467631, 2024).
glioma (continued). "To investigate how GINS2 affects the response of glioma cells to TMZ, we engineered SHG44 cells to overexpress GINS2 and knocked it out using clustered regularly interspaced short palindromic repeats (CRISPR)–Cas9 in U251 and LN229 cells, which highly express the protein." (PMID 38467631, 2024). "In this study, we performed ex vivo experiments to discover that GINS2 regulated the malignant phenotype and TMZ sensitivity of glioma cells, likely by promoting DDR through the early growth response protein 1 (EGR1)/ECT2 axis." (PMID 38467631, 2024). "By uncovering a novel mechanism by which GINS2 regulates the sensitivity of glioma to TMZ chemotherapy, these findings provide a promising genetic target for glioma treatment and inform the development of more effective therapeutic approaches." (PMID 38467631, 2024). "The mechanism by which GINS2 regulates the malignant phenotype and TMZ sensitivity of glioma is unclear." (PMID 38467631, 2024). "Therefore, GINS2 may be an essential biomarker for the diagnosis and prognosis of glioma." (PMID 38467631, 2024). "For example, the upregulation of GINS2 can promote the tumour progression of NSCLC, and the knockdown of GINS2 can inhibit the proliferation of human glioma cells." (PMID 36466552, 2022). "To determine whether GINS2’s regulation of the malignant phenotype and TMZ sensitivity of glioma was mediated by ECT2, we overexpressed ECT2 in GINS2 KO cells for rescue experiments." (PMID 38467631, 2024). "Therefore, the upregulation of ECT2 reversed the GINS2 KO-mediated reduction in proliferation, stemness, migration, invasion, and TMZ resistance of glioma cells." (PMID 38467631, 2024). "Furthermore, GINS2 regulated the malignant phenotype and TMZ sensitivity of glioma cells, mostly by promoting DNA damage repair by affecting the mRNA stability of early growth response factor 1 (EGR1), which in turn regulates the transcription of epithelial cell-transforming sequence 2 (ECT2)." (PMID 38467631, 2024). "In addition, the mRNA expressions of GINS2 and ECT2 were positively correlated in glioma." (PMID 38467631, 2024).
bladder cancer (6 papers, 2020 to 2023). "It turned out that knockdown of lncRNA SNHG3 inhibited GINS2, N‐cadherin and vimentin expression, and up‐regulated E‐cadherin expression of bladder cancer in vivo." (PMID 32596993, 2020). "The lncRNA SNHG3 promotes the progression of bladder cancer via the miR-515-5p/GINS2 axis." (PMID 34101736, 2021). "Yet, the role of GINS2 in the development of bladder cancer remains mysterious." (PMID 32596993, 2020). "Subsequently, we revealed that lncRNA SNHG3 enhances GINS2 expression via sponging miR‐515‐5p, thereby enhances the tumorigenesis and EMT in bladder cancer." (PMID 32596993, 2020). "Further investigation showed that SNHG3 significantly enhanced the proliferation, invasion, migration, and EMT of bladder cancer cells in vitro and in vivo through the regulation of GINS complex subunit 2 (GINS2), a member of the GINS complex involved in DNA replication, by “sponging” miR-515–5p." (PMID 36605618, 2023).
hepatocellular carcinoma (5 papers, 2021 to 2024). A malignant tumor that arises from hepatocytes. "Our results demonstrated the significance of GINS2 in the occurrence and progression of hepatocellular carcinoma and illustrated the association between the levels of GINS2 and prognosis as well as immune cell infiltration." (PMID 35069907, 2022). "Eventually, we found that CYP7A1/GINS2/PDLIM3 were associated with the prognosis of hepatocellular carcinoma (HCC) in the TCGA database." (PMID 34777484, 2021). "In hepatocellular carcinoma, up-regulation of GINS2 expression suggested a poorer prognosis and GINS2 may influence the extent of immune cell infiltration and thus the tumor microenvironment and ultimately altered the immune response." (PMID 37642814, 2024). "In terms of protein level, based on the analysis result of the CPTAC data set, the total GINS2 protein expression is higher in GBM, hepatocellular carcinoma, OV, PAAD, UCEC, and BRCA (P < 0.001)." (PMID 36466552, 2022).
thyroid cancer (5 papers, 2021 to 2023). "K-M survival analysis and subsequent multiple logistic regression revealed that the expression of BUB1 and GINS2 were potential risk factors for disease-free survival (DFS) of thyroid cancer." (PMID 37745716, 2023). "For example, a previous study found that inhibiting GINS2 expression promotes apoptosis of thyroid cancer cells by mediating the down-regulation of downstream proteins CITED2 and LOXL2." (PMID 36092720, 2022). "In recent decades, GINS2 has been involved in the development of various cancers, such as pancreatic, lung, and thyroid cancers." (PMID 34288816, 2021). "Compared with normal thyroid tissue, 7 CRGs were more highly expressed in thyroid cancer, namely BUB1 (P<0.001), RPL3 (P<0.001), TTK (P<0.001), GINS2 (P<0.001), SLC26A6 (P<0.001), CDKN2A (P<0.001) and ZNHIT2 (P<0.001)." (PMID 37745716, 2023). "GINS2 promotes cell proliferation and inhibits cell apoptosis by regulating CITED2 and LOXL2 in thyroid cancer." (PMID 34288816, 2021). "Evidence shows that GINS2 (GINS complex subunit 2) has a role in regulating cell cycle and apoptosis and is overexpressed in different malignant cancers, including pancreatic, lung and thyroid cancers." (PMID 35810383, 2022).